SYNCRIP (synaptotagmin binding cytoplasmic RNA interacting protein)
Diseases named in the same sentence as SYNCRIP in open-access papers:
SYNCRIP is named in the same sentence as 51 diseases in open-access papers, as found by Europe PMC text mining. Sharing a sentence is not in itself a finding about the gene and the disease. The quoted sentences say what the papers report.
colorectal cancer (5 papers, 2017 to 2024). A primary or metastatic malignant neoplasm that affects the colon or rectum. "In TCGA database, the ratio of SYNCRIP genetic alterations in colorectal cancer patients was around 3%." (PMID 39284825, 2024). "To explore the potential function of SYNCRIP in colorectal cancer, we first analyzed the expression of SYNCRIP using publicly available database TCGA (The Cancer Genome Atlas) and GEPIA (Gene Expression Profiling Interactive Analysis)." (PMID 39284825, 2024). "Taken all together, our results suggest SYNCRIP as a potent therapeutic target in colorectal cancer." (PMID 39284825, 2024). "Here, we found that SYNCRIP was highly expressed in colorectal cancer by analyzing TCGA and GEPIA database." (PMID 39284825, 2024). "Our results suggested SYNCRIP as a potential prognostic biomarker and therapeutic target in colorectal cancer." (PMID 39284825, 2024). "Taken all together, we investigated the important role of SYNCRIP in regulating colorectal cancer growth and motility in the present study." (PMID 39284825, 2024). "We are interested in the possible interaction between hnRNP Q (the synaptotagmin-binding cytoplasmic RNA interacting protein [SYNCRIP]) and LIN28 because abnormal levels of hnRNP Q have been implicated in several types of cancers, such as leukemia, liver cancer, and colorectal cancer." (PMID 38976670, 2024). "Our previous results showed highly expressed SYNCRIP in colorectal cancer cell, which suggested that SYNCRIP could play important role in CRC." (PMID 39284825, 2024). "However, two studies showed that one of the hnRNP Q isoform, hnRNP Q1, is involved in tumorigenesis via regulating cell cycle-related genes, such as Aurora-A in colorectal cancer, which suggested SYNCRIP as a key player in colorectal cancer development and pathology." (PMID 39284825, 2024). "In addition, the deregulation of SYNCRIP was found in colorectal cancer (CRC)." (PMID 39284825, 2024). "Moreover, SYNCRIP was confirmed to be a component of stress granules (SGs) in MDA‐MB‐231 human breast cancer and SW480 colorectal cancer cells." (PMID 32770626, 2020).
myeloid leukemia (5 papers, 2019 to 2025). A clonal proliferation of myeloid cells and their precursors in the bone marrow, peripheral blood, and spleen. "Previous studies have also identified SYNCRIP as a critical RNA-binding protein that regulates the leukemogenic transcriptional program in myeloid leukemia." (PMID 41294667, 2025). "SYNCRIP, an RNA-binding protein that controls the myeloid leukemia stem cell program, was found to be overexpressed after radiation and was duplicated in a patient with sarcoma." (PMID 32577795, 2020).
leukemia (4 papers, 2021 to 2024). A malignant (clonal) hematologic disorder, involving hematopoietic stem cells and characterized by the presence of primitive or atypical myeloid or lymphoid cells in the bone marrow and the blood. "The motifs in 3’UTR are among consensus binding sites for RBP MSI2, which we previously found to cooperatively work with SYNCRIP to drive translation of shared target genes in leukemia cells." (PMID 37085479, 2023). "Similar to MSI2, SYNCRIP was required for leukemia progression by utilizing an MLL-AF9 AML Syncrip knockout mouse model." (PMID 36307883, 2022).
Intellectual disability (3 papers, 2018 to 2025). "Mutations in both hnRNPU and SYNCRIP are linked to intellectual disability and neurodevelopmental disorders, and were the two top candidates in an IBM Watson-based study to identify RBPs altered in amyotrophic lateral sclerosis (ALS)." (PMID 39937575, 2025).
pancreatic cancer (3 papers, 2020 to 2025). "Targets of GTF3C1 and SYNCRIP, both of which are upregulated in metastatic pancreatic tumors compared to primary tumors, were also significantly increased in expression in high-ColX module gender-specific PAAD cohorts." (PMID 39939916, 2025). "Correlation analysis according to qRT‐PCR results showed that lncNT5E was positively correlated with SYNCRIP expression in pancreatic cancer tissues." (PMID 32770626, 2020). "Interestingly, SYNCRIP transcription, promoted by the lncNT5E, has a role in pancreatic cancer progression." (PMID 35055098, 2022).
viral infection (3 papers, 2014 to 2021). "The results show that SYNCRIP expression significantly increased with the doses of PPV infection, and the expression level of SYNCRIP is associated with viral infection level." (PMID 34034820, 2021). "Since the human hnRNP-Q homolog of LIF2, SNAP1/SYNCRIP, also acts as a cellular RBP and as a suppressor of human immunity against virus infection, our data highlight a conserved role for hnRNP-Q in eukaryote immunity." (PMID 24914891, 2014).
autism (2 papers, 2018 to 2023). Persistent deficits in social interaction and communication and interaction as well as a markedly restricted repertoire of activity and interest as well as repetitive patterns of behavior. "Genes located in proximal 6q that have been linked to autism are RIMS1 (regulating synaptic membrane exocytosis 1, MIM*606629), PHIP, SYNCRIP and ZNF292 (zinc finger protein 292, MIM*616213)." (PMID 29904178, 2018). "A patient with a 6q11 to 6q15 deletion was found to have severe developmental delay and autism, indicating that autism may be part of the SYNCRIP-related phenotype." (PMID 37371418, 2023). "This patient had severe developmental delay and autism, indicating that autism may be part of the SYNCRIP-related phenotype." (PMID 29904178, 2018).
autism spectrum disorder (2 papers, 2018 to 2024). A spectrum of developmental disorders that includes autism, and Asperger syndrome. "In total, 7/13 patients with a SYNCRIP deletion in our cohort had an autism spectrum disorder." (PMID 29904178, 2018). "Remarkably, we observed an autism spectrum disorder in 7/13 individuals with an HTR1E and a SYNCRIP deletion, while the numbers were 3/13 for RIMS1, 3/12 for HTR1B, 3/14 for PHIP and 4/10 for ZNF929." (PMID 29904178, 2018).
developmental delay (2 papers, 2018 to 2024). "Deletion of only PHIP or only SYNCRIP is enough to cause severe developmental delay, but most individuals with deletions of these genes show borderline to severe, or mild to severe developmental delay, respectively." (PMID 29904178, 2018). "The most influential gene on the neurodevelopmental phenotype seems to be SYNCRIP (6q14.3), while deletions that include more than two of these genes led to more severe developmental delay." (PMID 29904178, 2018). "Loss-of-function variants in SYNCRIP (synaptotagmin-binding cytoplasmic RNA-interacting protein, MIM*616686) have been detected in individuals with neurodevelopmental disorders and this might explain the more severe developmental delay seen in our subgroup C." (PMID 29904178, 2018).
hepatocellular carcinoma (2 papers, 2022 to 2024). A malignant tumor that arises from hepatocytes. "Coherently, SYNCRIP silencing in hepatoma cells modulated miR-122-5p, miR-181-a1-3p, and miR-181-b1-3p, allowing the rescue of the epithelial phenotype, and also determined let-7g-5p upregulation." (PMID 35055098, 2022). "Interestingly, we observed that SYNCRIP knockdown, in TGFβ-treated hepatocytes as well as hepatoma cells, leads to a significant modulation of both the pri and mature forms of the specific miRNAs investigated, thus indicating the conceivable involvement of this hnRNP in their transcription." (PMID 35055098, 2022).
liver cancer (2 papers, 2024). An epithelial or non-epithelial malignant neoplasm that arises from the liver. "Another hnRNP of interest is hnRNP Q (SYNCRIP), which is a negative prognostic indicator for liver cancer." (PMID 39336772, 2024).
prostate carcinoma (2 papers, 2024 to 2025). A carcinoma that arises from epithelial cells of the prostate gland. "In prostate cancer, the synaptotagmin-binding cytoplasmic RNA-interacting protein (SYNCRIP), which suppresses APOBEC-dependent mutagenesis, is frequently lost." (PMID 39624079, 2024). "Additionally, SYNCRIP has been reported to be involved in the tumorigenesis of prostate cancer and lung cancer." (PMID 41294667, 2025).
spinal muscular atrophy (2 papers, 2014). A motor neuron disease that affect the muscles, and characterized by muscle weakness and atrophy resulting from progressive degeneration and irreversible loss of the anterior horn cells in the spinal cord (i.e., lower motor neurons) and the brain stem nuclei. "Separate studies have also shown that SYNCRIP interacts with wild-type survival of motor neuron (SMN) protein but not the truncated or mutant forms found to cause spinal muscular atrophy, and Syp genetically interacts with Smn mutations in vivo." (PMID 25171822, 2014). "Furthermore, separate studies have revealed that SYNCRIP binds with wildtype Survival of Motor Neuron (SMN) protein, but not the truncated or mutants forms found in Spinal Muscular Atrophy, and Syp genetically interacts with Smn mutations in vivo." (PMID 25171887, 2014).
Cognitive impairment (1 paper, 2023). Abnormal cognition is characterized by deficits in thinking, reasoning, or remembering. "In addition, PRKCD, RASGRP1, SYNCRIP, CSNK1E, and CBX3 were involved in the regulation of synaptic plasticity and were associated with cognitive impairment caused by neurological diseases." (PMID 37106826, 2023).
colorectal tumor (1 paper, 2024). "To further confirm SYNCRIP as a therapeutic target, we tested the function of SYNCRIP on colorectal tumor cell growth in a mouse xenograft model." (PMID 39284825, 2024). "More importantly, our in vivo experiments showed that SYNCRIP depletion significantly inhibited colorectal tumor growth." (PMID 39284825, 2024).
fragile X syndrome (1 paper, 2014). A genetic syndrome caused by mutations in the FMR1 gene which is responsible for the expression of the fragile X mental retardation 1 protein. "Recent work has revealed that SYNCRIP/hnRNPQ and Fragile X mental retardation protein (FMRP) are present in the same mRNP granule, and loss of expression of FMRP or the ability of FMRP to interact with mRNA and polysomes can cause cases of Fragile X syndrome." (PMID 25171822, 2014).
Infertility (1 paper, 2025). "Similarly, SYNCRIP, by regulating the stability of cytokine mRNAs, could impact the intensity and duration of local inflammation, which is a hallmark of EMs and a driver of associated pain and infertility." (PMID 41168872, 2025).
influenza infection (1 paper, 2017). "The striking conservation of the expression of hnRNPs and SYNCRIP across 11 studies suggests that splicing is a significant process during influenza infection." (PMID 29214055, 2017).
Obesity (1 paper, 2026). Accumulation of substantial excess body fat. "Lastly, our study identifies several differently regulated proteins whose role in obesity and adipose tissue is poorly known, such as ANXA8, DDX39B, STX7, SYNCRIP, SYNGR2, and PAK2." (PMID 41077621, 2026).
ovarian carcinoma (1 paper, 2024). A malignant neoplasm originating from the surface ovarian epithelium. "Utilizing a lentiviral overexpression system, we demonstrated that elevated levels of SYNCRIP or SNU13 increased the resistance of ovarian cancer cells to cisplatin." (PMID 38898005, 2024).
cancer (14 papers, 2017 to 2025). A tumor composed of atypical neoplastic, often pleomorphic cells that invade other tissues. "The RNA-binding protein Q (hnRNP Q) or SYNCRIP (Synaptotagmin Binding Cytoplasmic RNA Interacting Protein) has been implicated in mRNA splicing, mRNA transport, translation, and miRNAs biogenesis as well as metabolism in cancer." (PMID 38976670, 2024). "Interestingly, some NDD hnRNPs have already been implicated in cell division through cancer studies, including hnRNPD, hnRNPK, SYNCRIP, and hnRNPU." (PMID 33874999, 2021). "Misregulation of SYNCRIP has been reported in neurodegenerative diseases, psychiatric disorders, and cancer." (PMID 33617535, 2021). "Conversely, knockdown of SYNCRIP or SNU13 significantly sensitized cancer cells to cisplatin." (PMID 38898005, 2024). "Some studies have reported that SYNCRIP expression plays an important role in cancers." (PMID 32770626, 2020). "Unlike other hnRNPs, hnRNP Q (also known as SYNCRIP) was less associated with cancer." (PMID 39284825, 2024). "Notably, a role for SYNCRIP in the development and differentiation of specific cell lineages has been described, as well as its aberrant regulation in different disorders, including cancers." (PMID 35055098, 2022). "We confirmed that various spliceosomal proteins (TIA1, SFSF4, SYNCRIP, and SNU13) can be secreted from dying cancer cells and transferred into recipient cells using GFP- and RFP- fusion constructs and subsequent confocal microscopy and western blotting." (PMID 38898005, 2024). "We further summarized six genes (IGF2BP3, LYAR, RALY, STAU1, SYNCRIP, and TOP1) that displayed high correlations between mRNA and protein expression in both cancer and cell line databases." (PMID 36428700, 2022). "Furthermore, the presence of SRSF4-RFP, SYNCRIP-GFP, and SNU13-GFP in extracellular vesicles was confirmed through flow cytometry analysis of CD9 positive extracellular vesicles from dying cancer cells." (PMID 38898005, 2024). "Despite this body of evidence, a link between SYNCRIP overexpression and the ability of cancer cells to metastasize has not yet been clarified." (PMID 35055098, 2022). "Moreover, the unique IHC staining of SYNCRIP and HNRNPU from BRCA could distinguish cancer tissues from normal tissues and help clinicians predict the clinical outcome." (PMID 33495416, 2021).
tumor (10 papers, 2009 to 2025). "The tumor size and weight were significantly decreased in SYNCRIP depletion group compared with control group." (PMID 39284825, 2024). "To further confirm the expression of SYNCRIP in CRC, we detected the mRNA and protein level of SYNCRIP in tumor tissue and adjacent normal tissues." (PMID 39284825, 2024). "In addition, we found that the mRNA and protein level of SYNCRIP was significantly higher in tumor tissue." (PMID 39284825, 2024). "Thus, SNU13 and SYNCRIP spliceosomal proteins promote therapy resistance, while the exogenous U12 and U6atac snRNAs stimulate tumor growth." (PMID 38898005, 2024). "Furthermore, we confirmed the expression of SYNCRIP expression in CRC tumor and CRC cell lines." (PMID 39284825, 2024). "We first analyzed the expression of SYNCRIP in TCGA and GEPIA database and found that the expression of SYNCRIP is significantly higher in CRC tumor compared with normal tissue." (PMID 39284825, 2024). "Altogether we would consider aberrations in SNX14, SYNCRIP, CBR3-AS1, and CKAP2 as putatively responsible for tumor development or being at least an important passenger aberration in the respective 1N patients." (PMID 32577795, 2020). "Thus, the respective oncogenic and tumor suppressor roles of IMP and SYNCRIP gene families appear to have been conserved in humans and they may not be restricted to tumors of neural origin." (PMID 31566561, 2019).
neurodevelopmental disorder (7 papers, 2018 to 2025). A behavioral and cognitive disorder with onset during the developmental period that involves impaired or aberrant development of intellectual, motor, or social functions. "One of the identified GUS, PPP1R12A, successively has been confirmed as disease‐gene of Genitourinary and/orbrain malformation syndrome (OMIM #618820), while a recent publication correlates SYNCRIP mutations in a new neurodevelopmental disorder." (PMID 38041506, 2023). "Of the 15 GUSs encountered, two have recently become disease genes: particularly, PPP1R12A gene has been associated with Genitourinary and/or brain malformation syndrome (OMIM #618820), while SYNCRIP gene is implicated in a new neurodevelopmental disorder." (PMID 38041506, 2023). "Additionally, the aRgus workflow could identify protein regions within functional domains that appear to be especially important in pathogenesis of a SYNCRIP-associated neurodevelopmental disorder and a gluconeogenesis defect caused by phosphoenolpyruvate carboxykinase deficiency." (PMID 36789265, 2023).
infection (2 papers, 2021). The state of being infected such as from the introduction of a foreign agent such as serum, vaccine, antigenic substance or organism. "Time-course experiments show that SYNCRIP mRNA significantly increased at 12 h post-infection (hpi) and reached the highest levels at 36 hpi." (PMID 34034820, 2021). "Knockdown of SYNCRIP resulted in significantly higher viral titers as determined by plaque assays, both at low and high multiplicity of infection (MOI)." (PMID 34541469, 2021). "Importantly, one of the partners identified, SYNCRIP, can protect against infection with the RNA virus, influenza A." (PMID 34541469, 2021). "To confirm whether SYNCRIP knockout decreased viral DNA replication via inhibition of the NS2 protein, we tested the relative viral titer of PPV or Y-PPVNS2− in PK-15 cells and SYNCRIP deficient cells depending on whether they express NS2 or not via infection with NS2 protein expressing lentivirus." (PMID 34034820, 2021). "Consistently, SYNCRIP protein levels varied in different tissues of control pregnant sows and also apparently increased in lung, kidney, ovary and uterus of PPV-infected pregnant sows at 35 days post-infection." (PMID 34034820, 2021). "The results show that the mRNA level of SYNCRIP in major targeted tissues (spleen, lung, kidney, ovary and uterus) increased compared to those in the nonpathological tissues (heart, liver and brain) of PPV-infected pregnant sows at 35 days post-infection (dpi)." (PMID 34034820, 2021).
immune dysfunction (1 paper, 2025). "For instance, small molecule inhibitors targeting HSP90B1 or agents that modulate SYNCRIP’s RNA-binding activity could be explored to simultaneously disrupt metabolic adaptation and correct immune dysfunction in EMs." (PMID 41168872, 2025).
SYNCRIP also shares sentences with these, for which no sentence is quoted: neurodegenerative disease (4 papers); neuroblastoma (2); rheumatoid arthritis (2); adult T-cell leukemia/lymphoma (1); Alzheimer disease (1); amyotrophic lateral sclerosis (1); Ataxia (1); brain cancer (1); brain tumor (1); breast carcinoma (1); Cerebral ischemia (1); Chiari malformation (1); colon cancer (1); glaucoma (1); lung carcinoma (1); lymph node metastases (1); medulloblastoma (1); myoclonic-atonic epilepsy (1); neurological diseases (1); oculopharyngeal muscular dystrophy (1); prion disease (1); psoriasis (1); psychiatric disorder (1); sarcoma (1); T-cell leukemia (1); toxoplasmosis (1).